INS (insulin)
Diseases named in the same sentence as INS in open-access papers (continued):
Sharing a sentence is not in itself a finding about the gene and the disease.
Insulin resistance (continued). "TNFα has been cited as being responsible for decreasing insulin sensitivity and contributing to insulin resistance in cancer." (PMID 30764482, 2019). "Although glucocorticoids induce insulin resistance (IR) in liver and muscle, they are known to sensitize insulin signaling in adipose tissues." (PMID 31322414, 2019). "In contrast, chronic administration of IL-6 has been found to induce insulin resistance, suppress glucose transport, and reduce insulin-induced lipogenesis." (PMID 31736870, 2019). "In this study, the demographic data showed that there was a correlation of insulin resistance with other biochemical parameters like glucose, insulin, and serum lipid profiles which were significantly different in the cases and controls." (PMID 31250990, 2019). "In order to combat insulin resistance, the body increases the production of insulin to maintain euglycemia leading to an increase in the size of islet cells and pancreatic β-cells." (PMID 31480505, 2019). "Insulin resistance is a condition in which insulin sensitivity is reduced and the insulin signaling pathway is impaired." (PMID 31258478, 2019). "Since insulin resistance is the main cause of T2DM, the insulin-related indicators were tested after 8 weeks of treatment." (PMID 32010641, 2019). "Obesity disturbs the fertility process not only by increasing oestrogen levels, but also as a consequence of increased insulin level and insulin resistance, which is manifested by an increase in the HOMA-IR index." (PMID 31288457, 2019). "Insulin resistance (IR) is considered an indicator of the inability of cells in muscle, fat, or liver tissue to respond to insulin, which in turn, limits the ability of the individual take up glucose from the blood easily." (PMID 31499737, 2019). "Since the decreased insulin sensitivity/insulin resistance is central for the progression of T2DM and its cardiovascular related complication, including DCM, induction of insulin resistance is highly desirable." (PMID 30343468, 2019). "Infusion studies show that the relationship between FFA and insulin resistance is dose-dependent, but the reduction in insulin sensitivity is detectable at levels that are well within the physiological range." (PMID 31920704, 2019). "Similar to the increased level of insulin in insulin resistance, the level of irisin in the plasma increased in MCI patients." (PMID 31572306, 2019). "A significant decrease level of vitamin D; has been reported also, glucose and phosphorus level in overweight obese women with PCOS correlated negatively with insulin and insulin resistance and positively with vitamin D level." (PMID 31814932, 2019). "Impaired insulin reaction with a diminution in skeletal muscle insulin delivery is a major aspect of obesity-induced insulin resistance." (PMID 31521172, 2019). "We evaluated the differential protein expression of adipose tissue from cows grouped according to insulin resistance or sensitivity following the evaluation of protein kinase B phosphorylation after insulin stimulation." (PMID 31766506, 2019). "Phosphorylation of intermediates in this pathway is required for insulin-stimulated GLUT4 translocation, and adipose-specific GLUT4 disruption causes insulin resistance." (PMID 31323977, 2019). "Endothelial dysfunction and insulin resistance are closely related phenomena, as it has been proposed that trans-capillary insulin transport is a rate-limiting step in peripheral insulin action." (PMID 31783601, 2019). "The therapies of insulin resistance can be classified based on their intended targets, including bile acid-based insulin sensitization, peroxisome proliferator-activator receptors, FGF21, and metformin." (PMID 30642126, 2019). "Given that the IR/Akt/mTOR pathway is a determinant of insulin sensitivity, galangin and pinocembrin are likely to abrogate insulin resistance in hepatocytes through modulation of the IR/Akt/mTOR pathway." (PMID 31805752, 2019).
Insulin resistance (continued). "In fact, transgenic mice that express in adipose tissues constitutive active human PPARα, presented under HFD, recovered insulin sensitivity, suggesting an important role of this NR in attenuating obesity-induced insulin resistance in WAT." (PMID 31683535, 2019). "Fasting insulin and glucose levels are currently used as important indicators for determining the presence of insulin resistance." (PMID 31300671, 2019). "The homeostatic model assessment–insulin resistance (HOMA-IR) index was widely used to estimate the insulin sensitivity." (PMID 31370285, 2019). "The inflammatory milieu heightens the expression and release of proinflammatory cytokines, such as TNFα and IL-1β, which play a key role in damnification of insulin signaling, leading to insulin resistance and subsequently promoting NAFLD." (PMID 31215394, 2019). "Potential mechanisms include modification to peripheral insulin signaling, exacerbated insulin resistance or impaired insulin secretion." (PMID 30816192, 2019). "Insulin resistance and elevation of circulatory insulin (hyperinsulinemia) that has been shown in PCOS patients leads to stimulation of androgen synthesis in adrenal and ovary via various mechanisms." (PMID 30944702, 2019). "Activation of the inflammatory cascade leads to the activation of serine kinases and the release of other molecules, such as galectin-3 and leukotriene B4 (LTB4), which directly decrease insulin sensitivity, thus resulting in insulin resistance." (PMID 31920976, 2019). "Insulin resistance describes a range of molecular phenotypes in which physiological regulatory functions of insulin are suppressed or altered." (PMID 31464373, 2019). "Patients and controls underwent anthropometric evaluation, measurement of fasting lipids, glucose, insulin, homeostasis model assessment for insulin resistance (HOMA-IR)." (PMID 30282618, 2019). "Type 2 diabetes mellitus (T2DM) is a chronic metabolic disorder, mainly characterized by hyperglycemia and pancreatic β-cell dysfunction, leading to insufficient insulin secretion and insulin resistance." (PMID 31156786, 2019). "It has been shown that TNF-α contributes to insulin resistance through impairment of insulin signaling by increasing serine phosphorylation of insulin receptor substrate- (IRS-) 1 and diminishing insulin receptor (IR) tyrosine kinase activity." (PMID 31828161, 2019). "GRE showed a strong potential to ameliorate hepatic insulin resistance by improving insulin sensitivity through the regulation of PI3K/AKT, FOXO1 and AMPK-mediated pathways." (PMID 30717198, 2019). "The occurrence of insulin resistance is explained by the existence of insulin antibodies, accelerated insulin degradation, and/or insulin transmission disorders." (PMID 31354904, 2019). "High blood glucose in the presence of raised serum levels of insulin indicates endocrine disruption caused by BPA; this type of metabolic abnormality is called the insulin resistance." (PMID 31217932, 2019). "Brain insulin resistance is defined as a state of reduced brain responsivity to insulin stimulation." (PMID 29736736, 2019). "On the contrary, adolescents with a high dietary fiber intake showed significantly lower prevalences of insulin resistance (9.7%) and abnormal insulin levels (8.3%) than those with the lowest fiber intake (34.3% and 35.6%, respectively)." (PMID 31888175, 2019). "The precise contributing factors for a given individual vary, but generally include a combination of insulin resistance and insufficient insulin secretion." (PMID 31258514, 2019). "Kernel oil of WP improved hyperglycemia, insulin resistance and insulin secretion, but the changes in oxidative stress markers, liver enzymes and histopathologic results were not significant among the groups." (PMID 34466477, 2019). "Insulin resistance is a state in which physiological amount of insulin has a reduced effect on post-prandial glicemic control with an inadequate insulin suppression during the night period." (PMID 30885221, 2019).
Insulin resistance (continued). "In human studies, individuals with severe insulin resistance had higher resistin levels than individuals with normal insulin action." (PMID 31803062, 2019). "T1DM is due to an impaired insulin production, while T2DM is caused by a combination of genetic and environmental factors, which lead to insulin resistance and impaired insulin secretion." (PMID 31534451, 2019). "Despite the prevalence of insulin resistance in older individuals, there is little data regarding how sex and age interact with respect to insulin action." (PMID 30706674, 2019). "Insulin resistance (IR) refers to a pathophysiologic condition in which there is a decrease in insulin-mediated glucose uptake and utilization in insulin-sensitive tissues and cells such as the liver, skeletal muscle, and fat tissues and cells." (PMID 31218568, 2019). "In male mice, overexpression of angiotensinogen in adipose tissue results in hypertension, increased adiposity, insulin resistance, glucose intolerance, and reduced insulin-stimulated skeletal muscle glucose uptake." (PMID 31262355, 2019). "The reduction in the responsiveness of tissues to the normal action of insulin is referred to as insulin resistance." (PMID 31976027, 2019). "From a metabolic standpoint, prenatal co-treatment with an insulin sensitizer successfully prevented the development of insulin resistance in prenatal testosterone-treated sheep, restoring mean insulin and insulin/glucose ratio during a glucose tolerance test." (PMID 31336724, 2019). "T2D is a major metabolic disorder, which is characterised by increased blood sugar as a result of insulin resistance and due to reduced insulin secretion from pancreatic beta cells." (PMID 31685799, 2019). "For example, literature confirms that decreased insulin secretion capacity takes a bigger role in the development of T2D in the Japanese population than insulin resistance." (PMID 31216985, 2019). "In contrast, mice heterozygous for Pparg+/- displayed greater insulin sensitivity than the wild-type animals and improved insulin resistance and obesity." (PMID 31266232, 2019). "SEPT11 mRNA was positively correlated with markers of insulin resistance in adipose tissue, and silencing of septin-11 muted insulin signaling and insulin-induced lipid accumulation in adipocytes." (PMID 31105878, 2019). "It is generally accepted that Ad is negatively related to insulin levels due to its anti-insulin resistance effects." (PMID 31191339, 2019). "Fully differentiated adipocytes were treated with 1 μM DEX for 48 and 96 h to induce insulin resistance, leading to significantly reduced glucose consumption after insulin stimulation (P<0.01) compared with control cells." (PMID 30886061, 2019). "Glucose metabolic parameters included glycosylated hemoglobin (HbA1c), plasma glucose (PG), C-peptide (CP), insulin (INS), and the indices of β-cell function, insulin sensitivity, and insulin resistance (IR)." (PMID 31736874, 2019). "This points to tissue-specific responses within the insulin-signaling pathway that lead to the observed global insulin resistance." (PMID 31531397, 2019). "An insulin resistance model was established by exposing mature adipocytes to excessive glucose and insulin." (PMID 31828146, 2019). "Based on our results we suggest that, in 1 mg/kg dose, diosgenin has an insulin sensitizing effect, but in 10 mg/kg dose it promotes insulin resistance." (PMID 31080828, 2019). "There is a possibility that differences in blood glucose levels seen in CX3CR1−/− and IL-1a/b KO mice compared to WT following insulin administration are rather due to insulin resistance than impaired counterregulatory responses." (PMID 30996341, 2019). "Maternal whole blood glucose, serum leptin and insulin concentrations, and homeostatic model assessment of insulin resistance (HOMA-IR) were all higher in high-fat fed dams compared to controls." (PMID 31772245, 2019).
Insulin resistance (continued). "Higher ALT concentrations were also associated with insulin resistance and worse metabolic profile (higher HOMA-IR, glucose, insulin, triglyceride concentration, and lower HDL-C concentration)." (PMID 30987010, 2019). "These events alter insulin responsiveness of liver, skeletal muscle and adipose tissue exacerbating whole body insulin resistance." (PMID 30906281, 2019). "The insulin tolerance test at 15 months of age demonstrated that HFD-induced insulin resistance was improved in both HFD-Chow and HFD-CR mice." (PMID 30975165, 2019). "Recent data indicate a positive correlation of ANGPTL3 with plasma glucose, insulin, and homeostatic model assessment of insulin resistance (HOMA-IR) in insulin-resistant states." (PMID 30944669, 2019). "Body weight, glucose, lipid, insulin, epididymal fat pad and liver weights, and histologic characteristics were evaluated to determine the effect on insulin resistance." (PMID 30744038, 2019). "Further examinations including insulin resistance and insulin secretion ability during pregnancy and efforts to understand the cause of GDM will ensure the future health of pregnant women." (PMID 31275653, 2019). "Increased hepatic FFA induces increased hepatic lipogenesis and gluconeogenesis, as well as decreased insulin clearance, resulting in hyperinsulinemia and insulin resistance." (PMID 31835303, 2019). "It has been suggested that mTOR activation is required for SREBP-1c activity related to lipogenesis, particularly related to insulin-mediated activity in the case of insulin resistance." (PMID 30871035, 2019). "The β-glucan content in oat fiber was 22%, and our previous investigation demonstrated that oat fiber was more effective in improving insulin resistance and increasing insulin sensitivity." (PMID 30863273, 2019). "Our study, demonstrating the activation of insulin signaling cascade by a botanical preparation of Sarcopoterium spinosum root extract, is important in view of the search for new agents to fight insulin resistance." (PMID 31234331, 2019). "Insulin levels are higher than normal, but inadequate to overcome insulin resistance due initially to inappropriate glucagon secretion and to the lipo-toxicity that is characterized by greater triacylglycerol storage in non-fat tissues." (PMID 31781045, 2019). "Pancreatic β-cell dysfunction, where β-cells are unable to compensate for the degree of insulin resistance by over-secreting insulin, is another key factor in the pathophysiology of T2DM." (PMID 30987356, 2019). "Insulin resistance results in increased insulin secretion from the pancreas to try to compensate and maintain glycemic control." (PMID 30809194, 2019). "Insulin is the only hormone capable of reducing blood glucose level, and insulin resistance is a commonly observed phenomenon in type 2 diabetes patients." (PMID 30704063, 2019). "Comparable to human NAFLD patients, we observed that rats on an HFD developed insulin resistance (IR), as shown by elevated plasma insulin levels with the HFD." (PMID 31060228, 2019). "Insulin resistance with an inadequate insulin secretory response is the etiology of type 2 diabetes mellitus (T2DM; Umar, Ahmed, Muhammad, Dogarai, & Soad, 2010)." (PMID 30680174, 2019). "Alterations in peripheral glucose metabolism due to insulin resistance (IR) were assesed by HOMA-IR (Glucose x Insulin/22.5), while adipose tissue IR was estimated as (Adipo-IR = Free Fatty Acids x Insulin)." (PMID 31888144, 2019). "Because insulin resistance plays a fundamental role in the pathogenesis of T2D, interventions aimed towards improvement in insulin sensitivity should play a critical role." (PMID 31242682, 2019). "It has also been reported that eating an HFD leads to chronic inflammation that presents as infiltration by pro-inflammatory macrophages, which in turn leads to insulin resistance in peripheral insulin-responsive tissues, including adipose tissue and liver." (PMID 31756626, 2019).
Insulin resistance (continued). "Some of the mechanisms are an alteration in gonadotropin releasing hormone (GnRH) secretion, increase of luteinizing hormone (LH) secretion, and alteration in insulin secretion which leads to hyperinsulinemia and insulin resistance (IR)." (PMID 30863446, 2019). "The parameters of DM, including fasting blood glucose, glycated hemoglobin, insulin, and C-peptide levels, and homeostatic model assessment-insulin resistance index, significantly improved 1 year after SG (p < 0.05)." (PMID 31181641, 2019). "In this context, it is relevant to mention that T2D is characterized by insulin resistance and that insulin release is stimulated mainly by hyperglycemia." (PMID 31487953, 2019). "A pulse-based diet was superior to a hospital diet for maintaining insulin sensitivity, preventing insulin resistance, attenuating bone resorption and decreasing diastolic blood pressure during four days of bed rest." (PMID 31461862, 2019). "Continuous insulin resistance will progress to T2DM when β-cells are unable to secrete adequate insulin to compensate for the decreased insulin sensitivity, which is largely due to insulin secretory dysfunction of β-cells." (PMID 31097962, 2019). "The basic pathogenesis of T2DM is characterized by hyperglycemia, relative impairment in insulin secretion, and insulin resistance." (PMID 31215434, 2019). "For example, treatment with phytoestrogens in postmenopausal women with type 2 DM reduced fasting insulin and insulin resistance after 12 weeks of treatment." (PMID 31671813, 2019). "Secondary outcomes include 2-hour blood glucose, fasting insulin, homeostatic model assessment for insulin resistance, incidence of diabetic complications, and acupuncture-related adverse events." (PMID 30633207, 2019). "Adipose tissue macrophages (ATMs) are primary sources of proinflammatory cytokines such as TNF-α and IL-6, which suppress insulin action and induce the development of insulin resistance." (PMID 31551782, 2019). "Impaired responsiveness to insulin evokes insulin resistance in NAFLD, hence, the improvement of insulin sensitivity is important for the treatment of NAFLD." (PMID 31803542, 2019). "This study demonstrated that metformin monotherapy after intensive insulin therapy significantly reduced the overall bodyweight and BMI and improved insulin resistance and dyslipidemia in T2DM patients." (PMID 31073335, 2019). "The fatty acid receptors distributed in per unit area of islet cells are relatively reduced, will decrease insulin sensitivity, reduce insulin action, induce excessive secretion of insulin and result in insulin resistance and dysfunction of pancreatic β-cell." (PMID 31362999, 2019). "The reason for this decreased insulin signaling was proposed to be mediated by NFkB, suggesting that inflammation plays a role in EV-induced insulin resistance." (PMID 30857250, 2019). "If insulin resistance is present in pancreatic α cells, these insulin signals are attenuated and affect glucagon secretion." (PMID 31357734, 2019). "Previous reports have showed elevated decorin gene expression coupled with increased circulating insulin levels and insulin resistance in rodents and humans." (PMID 30874564, 2019). "Homeostasis model assessments of fasting insulin resistance, the Matsuda Index, the insulinogenic index, and the disposition index were assessed by plasma glucose and serum insulin concentration obtained at fasting or during an OGTT." (PMID 31690291, 2019). "Initially, islet β cells increase insulin secretion to meet insulin demand, but gradually they cannot compensate for insulin resistance, and hypoinsulinism and hyperglycemia appear." (PMID 31066759, 2019). "Inhibition with PI3Kα-specific inhibitors (PIK-90, PI-103, or PIK-75) blocked insulin-stimulated glucose uptake in vivo, resulting in insulin resistance." (PMID 31443495, 2019).